PRSS8 (serine protease 8)
Diseases named in the same sentence as PRSS8 in open-access papers (continued):
Sharing a sentence is not in itself a finding about the gene and the disease.
cancer (continued). "In addition, PRSS8 expression was reduced in the cancers of prostate, breast, bladder and stomach, showing tumor suppressive roles." (PMID 27081034, 2016). "In addition, the stroma of cancer in situ showed more expression of PRSS8 compared to that in invasive ESCC stroma (p=0.017)." (PMID 27081034, 2016). "Interestingly, ESCC stromal expression of PRSS8 was significantly correlated with stromal lymphocyte infiltration and cancer progression." (PMID 27081034, 2016). "It is worthy to be noted that the positive correlation of stromal expression of PRSS8 and lymphocyte infiltration could be resulted from a feedback or response, suggesting that PRSS8 acts as a protector or suppressor to prevent cancer invasion and progression." (PMID 27081034, 2016). "The PRSS8 gene was overexpressed in the majority of cancer types tested." (PMID 27036110, 2016). "However, controversy emerged to indicate that PRSS8 can act as a tumor suppressor in other cancers." (PMID 34823420, 2021). "Thus, the positive correlation of PRSS8 expression and lymphocyte infiltration in the ESCC stroma could be resulted from a feedback or response to prevent cancer cell invasion and limit cancer metastasis, therefore these findings provides additional evidence of tumor suppression role of PRSS8." (PMID 27081034, 2016). "We have shown that a glycosylphosphatidylinositol (GPI)-anchored epithelial extracellular membrane serine protease, prostasin/PRSS8, modulates EGFR signalling via enhancement of matriptase cleavage of the EGFR extracellular domain (ECD), and regulates SLUG and E-cadherin expression in cancer cells." (PMID 19849847, 2009).
tumor (20 papers, 2012 to 2025). "PRSS8 encodes a glycosylphosphatidylinositol (GPI)-anchored serine protease that acts as a tumor suppressor." (PMID 40723891, 2025). "Several DEGs have been demonstrated to be associated with tumor development, including protease serine 8 (PRSS8), claudin 7 (CLDN7) and Ras-related protein Rab-25 (RAB25)." (PMID 25351113, 2015). "Mechanistic study showed that tumor inhibition of PRSS8 may be associated with proliferation- and epithelial mesenchymal transition - related proteins in ESCC cells." (PMID 27081034, 2016). "In vivo, conditional knockout of Prss8 in mice leads to spontaneous intestinal inflammation and tumor formation, while PRSS8 overexpression suppresses tumor growth, invasion, and metastasis." (PMID 40723891, 2025). "PRSS8 has been described as a potent tumour suppressor in colorectal carcinogenesis and metastasis and is normally secreted to the extracellular space to be part of the seminal fluid." (PMID 40276932, 2025). "Through analysis, our study demonstrated the tumor-promoting properties of circ_0001741 in OC and pointed out the existed circ_0001741/miR-491-5p/PRSS8 axis in OC progression." (PMID 39527152, 2024). "Circ_0001741, miR-491-5p, and PRSS8 levels in OC tumor tissues and cells were quantified by quantitative real-time PCR or western blot." (PMID 39527152, 2024). "In conclusion, circ_0001741 silencing inhibited OC tumor growth by regulating miR-491-5p/PRSS8 pathway." (PMID 39527152, 2024). "Given that miR-24-3p inhibition leads to increased apoptosis, we predict that HMOX1 and PRSS8 function as tumor suppressors in CRC." (PMID 36457077, 2022). "Multivariate Cox regression analysis in the TCGA-BLCA dataset revealed that the expression levels of EMP1, RASGRP4, AHNAK, SLC1A6, and PRSS8 in tumor tissues were independent predictors for the unfavorable prognosis of BUC patients." (PMID 34905506, 2021). "Since PRSS8 exerts tumor inhibition functions in ESCC cells, we then determined the potent mechanism." (PMID 27081034, 2016). "Taken above, these findings strongly suggested that PRSS8 has tumor suppression functions and PRSS8 promoter hypermethylation has important significance." (PMID 27081034, 2016). "To determine tumor suppressive roles of PRSS8 in vivo, we established a stable PRSS8 overexpression HCT116 cell line, and injected these cells subcutaneously in nude mice." (PMID 27050145, 2016). "Results showed that PRSS8 was overexpressed in HCT116 tumor cells which were transfected with PRSS8 plasmid, and that PRSS8 was almost undetectable in the tumor cells that were transfected with empty vector." (PMID 27050145, 2016). "In all tumor subtypes examined, the neighboring stromal compartment exhibited low basal level staining, suggesting predominant expression of PRSS8 in tumor epithelium." (PMID 27036110, 2016). "Overexpressing PRSS8 significantly inhibited tumor growth in mice, resulting in significant retardation of tumor size and tumor weight." (PMID 27050145, 2016). "In conclusion, PRSS8 acts as a tumor suppressor by inhibiting Sphk1/S1P/Stat3/Akt signaling pathway, and could be used as a biomarker to monitor colorectal carcinogenesis and predict outcomes." (PMID 27050145, 2016). "The study design was to monitor the epigenetic changes in two tumor suppressor genes, RUNX3 and PRSS8, and follow up with a screening for epigenetic changes in more tumor suppressor genes if CSE-induced changes were to be observed in the RUNX3 and PRSS8 marker genes." (PMID 23724145, 2013). "Notably, PRSS8 was significantly overexpressed in tumour samples from poor-responders." (PMID 41290592, 2025). "However, the restored PRSS8 and its tumor inhibition could be reversed by small interfering RNA targeting PRSS8." (PMID 27081034, 2016). "A comparative analysis revealed that five sodium ion transport-related genes—FXYD2, ANK3, ATP1A1, PRSS8, and CHP1—were significantly downregulated in malignant cells, implicating their potential involvement in tumor suppression." (PMID 40723891, 2025).
tumor (continued). "Eight genes exhibited greater than 340-fold increases in expression in tumor tissues (CLDN6, KLK7, WNT10A, MYBL2, MAL2, KRT7, PRSS8, EPCAM; Median (Range) of fold increase = 344 (261–7267))." (PMID 41465326, 2025). "The mRNA expression levels of AHNAK, EMP1, RASGRP4, and HSPA1L were significantly down-regulated in BUC tumor tissues compared with normal tissues while SLC1A6 and PRSS8 were significantly up-regulated (P < 0.05)." (PMID 34905506, 2021). "Observation from tumor tissues of mice showed that the tumor tissues of mice with low SREBF2 expression were significantly reduced, while those mice with further overexpression of PRSS8 showed an increased tendency." (PMID 34823420, 2021). "For example, the serine proteases PRSS3 (also known as trypsinogen IV), PRSS8 (prostasin), and PRSS21 (testisin) were categorized as tumor-protective proteases in the human degradome." (PMID 22761798, 2012). "Western blot was used to detect the expressions of SREBF2, PRSS8 and SCNN1A in tumor tissues." (PMID 34823420, 2021). "Interestingly, tumor inhibition by DAC-mediated restoration of PRSS8 was reversed by small interfering RNA targeting PRSS8, for instance, cell proliferation, motility and migration in the DAC+siR-PRSS8 groups were similar as in the control groups in KYSE450 and EC9706 cells." (PMID 27081034, 2016).
benign tumors (1 paper, 2018). "Of these, 15 proteins (PRSS8, MK, WFDC2 (HE4), IL-10, SOD2, PARP-1, hK11, PVRL4, MUC-16 (CA125), FR-alpha, CDH3, NTRK3, IL-8, IL-17C, EN-RAGE) were selected from the comparison between OC stage I–IV and benign tumors." (PMID 30519148, 2018).
kidney disease (1 paper, 2025). "Renin, GDF15, PRSS8, RARRES2, PGLYRP1, LOX1, and UPAR, all robustly related to PA, have been related to cardiovascular or kidney disease via different pathways." (PMID 40498722, 2025).
PRSS8 also shares sentences with these, for which no sentence is quoted: adenocarcinoma (2 papers); Alzheimer disease (2); amyotrophic lateral sclerosis (1); asthenozoospermia (1); colorectal (1); ichthyosis (1); multiple sclerosis (1); osteogenesis imperfecta (1); pancreatic cancer (1); Parkinson disease (1); prostate adenomas (1); steatosis (1); stomach cancer (1).